AGO2 (argonaute RISC catalytic component 2)
Diseases named in the same sentence as AGO2 in open-access papers (continued):
Sharing a sentence is not in itself a finding about the gene and the disease.
tuberculosis (1 paper, 2021). A chronic, recurrent infection caused by the bacterium Mycobacterium tuberculosis. "As for M.tb infection, single nucleotide polymorphisms (SNPs) of AGO2 have also been found linked with tuberculosis susceptibility in the Chinese Uygur population." (PMID 34632719, 2021).
viral hepatitis (1 paper, 2024). An acute or chronic inflammation of the liver parenchyma caused by viruses. "In viral hepatitis, AGO2 enhances HBV replication by interacting with miR-146a and aids HCV RNA stability through miR-122." (PMID 39119295, 2024).
Williams-Beuren syndrome (1 paper, 2015). "Such functions are also known for the genes that are ECpiC loci, such as the oncogenic transcription factors ABL2 and ELK4, the miRNA effector AGO2, and TBL2 and KCTD7 genes that are in the deleted locus of Williams-Beuren syndrome patients, which display developmental defects." (PMID 26588211, 2015).
tumor (157 papers, 2007 to 2026). "Both Ago2 and its associated miRNAs (e.g., miR-3613-3p) are actively sorted into cancer cell– or tumor-derived EVs in an Ago2/CAV1 interaction manner." (PMID 38649663, 2024). "The elevated EV miRNA-3613-3p in the plasma of tumor-bearing mice is associated with Ago2/CAV1 interaction in the tumor cells." (PMID 38649663, 2024). "Of note, the observation from the treatments of cisplatin/Pep#11/Pep#26 showing significantly greater tumor suppressive effects than cisplatin alone implicated a potential of conquering chemoresistance when MSI1/AGO2 interaction was disrupted." (PMID 35158774, 2022). "Epidermal growth factor receptor (EGFR), for instance, was demonstrated to enhance its oncogenic role in cancer progression by suppressing microRNA (miRNA) maturation of tumor suppressors when associated with phosphorylated AGO2 under hypoxia." (PMID 35158774, 2022). "In particular, the small molecule TPE, which inhibits the association between AGO2 and miRNAs, was shown to suppress growth of 3T3 mouse embryonic cells and completely inhibit tumor formation in mouse models in vivo." (PMID 33668654, 2021). "Taken together, these findings suggest that the expression levels of tumor-suppressive miR-185-3p are associated with the intracellular levels of AGO2 and that NRP1 is a direct target of miR-185-3p in CRC cells." (PMID 33846300, 2021). "The underlying mechanism of tumor-suppressor miR-193b-3p and -5p was explored using reverse transcriptase quantitative polymerase chain reaction (RT-qPCR), Western blot, Argonaute 2-RNA immunoprecipitation (Ago2-RIP), and reporter assays." (PMID 31262974, 2019). "Tumor formation assay showed that knockdown of AGO2 caused remarkable inhibition on tumor growth in nude mice (P<0.0001)." (PMID 28903378, 2017). "hMex-3A and 3B are also associated with Argonaute (Ago) proteins (Ago1 and Ago2) which are the key components of the RNA-induced silencing complex and have been implicated in tumor development." (PMID 28977858, 2017). "AGO2 can directly bind to the promoter of focal adhesion kinase, which is a critical molecule associated with tumor metastasis, and can trigger its transcription." (PMID 28589097, 2017). "In BC, where AGO2 has been shown to be associated with tumor progression, ERβ inhibits cancer cell proliferation and tumor growth and its expression has been found to correlate with a better prognosis of the disease." (PMID 29017520, 2017). "Therefore, the plasma membrane association of Ago2 in tumor cells depends on the Ago2/CAV1 interaction mediated by the CBM of Ago2." (PMID 38649663, 2024). "The mechanisms underlying these two opposite functions of Ago2, which promote or inhibit tumor growth, remain unknown." (PMID 35459267, 2022). "In contrast, AGO2 expression was found to be higher when SNP rs3928672 was present in nasopharyngeal cancers, and the SNP was associated with a significantly increased risk of the disease and with tumour promoting properties." (PMID 36497229, 2022). "Surprisingly, mice aged over 400 days showed significantly increased pancreatic weights in both the AGO2+/+;KRASG12D;p48Cre and AGO2fl/+;KRASG12D;p48Cre cohort compared with AGO2fl/fl;KRASG12D;p48Cre mice, suggestive of a higher tumor burden in mice with at least one functional allele of AGO2." (PMID 32499547, 2020). "A miRNA dependent role for Ago2 has been established in tumorigenesis and its miRNA-independent roles have been linked to cancer initiation/progression through interactions with known tumour promoting factors (FAK, SWI/SNF, KRAS)." (PMID 31324173, 2019).
tumor (continued). "AGO2 can regulate neovascular formation by abnormally modulating angiogenic associated miRNAs and most of the time can act as an oncogene in human carcinogenesis by promoting tumor growth." (PMID 28903378, 2017). "Here, we identify TRIM25 as a key driver of tumor progression and chemoresistance by promoting the destabilization of AGO2." (PMID 42062253, 2026). "In the TCGA CRC dataset, we observed JUP and AGO2 exhibited upregulated expression in tumor tissues compared with normal tissues." (PMID 41583504, 2026). "Genetic deletion of Ago2 in cancer cells restores interferon signaling and supports immune infiltration of the tumor." (PMID 42313870, 2026). "By interacting with AGO2, they induce the assembly of the RNA-induced silencing complex (RISC), suppress the activation of tumor-associated signaling pathways, and thereby inhibit the proliferation and metastasis of BC cells." (PMID 40001986, 2025). "Investigating the functional significance of the radiation-induced decrease in the AGO2-Let-7 binding revealed that preventing the reduction in AGO2 bound Let-7 miRNAs using Let-7a mimics increased tumor cell radiosensitivity." (PMID 40943404, 2025). "Previously, we revealed that QKI promotes AGO2/let-7b-mediated gene silencing and functions as a tumor suppressor in HeLa cells." (PMID 39308343, 2024). "Blocking Ago2/CAV1 interaction in cancer cells decreases the dissemination of primary tumor cells in the lungs." (PMID 38649663, 2024). "The Weiss score, which reflects tumor aggressiveness, further confirmed this finding, with higher scores correlating with elevated AGO2 expression (gene P = 0.003, protein P = 0.008)." (PMID 39404265, 2024). "Confocal immune staining indicates that Ago2 co‐localizes with Trp, and that a much stronger interaction signal is detected in adjacent normal tissue than in tumor tissue." (PMID 39031551, 2024). "Given that Ago2/CAV1 interaction is required for the dissemination of primary tumor cells in the lungs, we investigated the role of Ago2/CAV1 interaction in lung targeting of circulating cancer cells, the early stage of metastasis." (PMID 38649663, 2024). "Increased Ago2/CAV1 interaction with tumor progression promotes aggressive behaviors, including metastasis and EV miRNA release." (PMID 38649663, 2024). "Ago2 was distributed either in the entire tumor cells (#7512, #8364, #8549, #9455, #10482, and #10549) or in the nuclei of tumor cells (#7194 and #9456) in primary tumors." (PMID 38649663, 2024). "By contrast, in metastatic tumor cells in lymph nodes, Ago2 was located at the plasma membrane, labeled with anti-cytokeratin (8/18) antibodies (Fig. EV4Aiv)." (PMID 38649663, 2024). "Increased Ago2/CAV1 interaction with tumor progression promotes aggressive cancer behaviors, including metastasis." (PMID 38649663, 2024). "Blocking Ago2/CAV1 interaction attenuates the metastatic tumor formation of circulating cancer cells in the lungs and other organs." (PMID 38649663, 2024). "Recently, a report showed a shift from exclusively cytoplasmic to ubiquitous localization of AGO2 in normal vs. malignant colon tissues, suggesting possible tumor-promoting functions of nuclear localized AGO2." (PMID 38994560, 2024). "The second activates astrocytes and suppresses miR-204-3p expression in an Argonaute-2 (Ago2)-dependent manner, promoting tumor invasive and migratory mechanisms." (PMID 39684236, 2024). "AGO2 nuclear localization is observed in tumor tissue from some patients, and the impact of shifting the localization of RNAi factors and reducing miRNA repression on cancer progression merits further exploration." (PMID 38109320, 2024). "We performed RNA immunoprecipitation (RIP) for argonaute 2 (AGO2) in tumor cells and investigated the expression of circ_0009092 and miR-665 by qPCR to verify the binding effect between circ_0009092 and miR-665." (PMID 38008713, 2023).
tumor (continued). "The m7GRGs AGO2, EIF4E3, DCPS and EIF4E have been extensively studied, and some of them have been associated with tumour progression." (PMID 37353728, 2023). "Circulating tumor miRNAs (ct-mirRNAs) are more stable compared with other extracellular RNAs: they are complexed with proteins or lipoproteins such as Argonaute 2 (AGO2), or packaged inside EVs which protect them against RNase activity." (PMID 36835424, 2023). "To explore a potential broad regulatory function of MLL4 in AGO2 expression in human tumor cells, we analyzed the expression correlation between the mRNA levels of MLL4 and AGO2 in the TCGA human tumors and the CCLE) human tumor-cell lines." (PMID 36323669, 2022). "This mimicking ability of Pep#11 and Pep#26 resulted in interference to endogenous MSI1/AGO2 interaction, thereby impairing cellular survival and tumor progression in GMB and PDAC animal models." (PMID 35158774, 2022). "Most of these miRNAs have tumour suppressive functions in healthy cells, making the phosphorylation of AGO2 tumour promoting." (PMID 36497229, 2022). "As a result, Pep#11 and Pep#26 were identified in the arrays and were demonstrated to be effective in not only the MSI1/AGO2 complex disruption in vitro, but in vivo as well where the tumor suppression capability was delineated." (PMID 35158774, 2022). "Overexpression of the C-terminus of MSI1 disrupts endogenous MSI1/AGO2 interaction and effectively reduces stress-induced tumor progression." (PMID 35158774, 2022). "Attenuation of Ago2 expression partially accounts for the increased tumor immunogenicity and the augmented immune response to Mll4−/− tumor cells, probably through interfering with dsRNA homeostasis and eliciting interferon responses." (PMID 36323669, 2022). "These pronounced tumor suppression effects exerted by synthetic Pep#11/Pep#26 were likely attributed to the blockade of the oncogenic functions of the endogenous MSI1/AGO2 complex in cancer cells." (PMID 35158774, 2022). "The proliferative capability of Saos2 cells was significantly increased after Ago2 depletion, suggesting that Ago2 suppresses cell growth as a tumor suppressor." (PMID 35459267, 2022). "Intriguingly, we found MLL4 depletionleads to a prominent reduction in both transcript and protein levels of AGO2 in B16 tumor cells and a few examined human cancer lines." (PMID 36323669, 2022). "Studies on the role of AGO2 associated with AC003101.2 in tumorigenesis and tumor progression have matured." (PMID 36185235, 2022). "Mechanistically, the seeming paradox regarding a tumor-suppressive versus oncogenic function of Ago2 and p63 isoforms can be reconciled in different tissue contexts." (PMID 35459267, 2022). "For instance, elevated miR-25 in NPC cells can bind to the metastasis associated lung adenocarcinoma transcript 1 (MALAT1) for directly silencing it in an Argonaute2 (Ago2)-dependent degradation, thereby inhibiting tumor progression." (PMID 35541920, 2022). "As a key component of the RNA-induced silencing complex (RISC), Argonaute2 (Ago2) exhibits a dual function regulatory role in tumor progression." (PMID 35459267, 2022). "The tumorigenic properties of AGO2 through inhibition of target mRNA maturation of tumor suppressors were also established by elevated AGO2 expression in various cancers in addition to GBM." (PMID 35158774, 2022). "RIP results showed that miR-197 and hsa_circ_0039569 were enriched in Ago2 immunoprecipitates, indicating their interaction in tumor cells." (PMID 35130798, 2022). "In chemoresistant patients, tumour expression of miR-2392 was increased and partially regulated transcription of mitochondrial genes in a splicing-competent Argonaute 2 (AGO2)-dependent manner." (PMID 35887244, 2022). "We show that p63 is a crucial regulator of Ago2 that functions as a tumor suppressor or as an oncogene." (PMID 35459267, 2022).
tumor (continued). "Under hypoxic stress, epidermal growth factor receptor (EGFR) suppresses the maturation of specific tumor-suppressor miRNAs by phosphorylation of argonaute 2 (AGO2)." (PMID 33898432, 2021). "Most of these tumor miRNAs circulate in the blood as stable complexes with Ago2 protecting miRNAs from degradation." (PMID 33435285, 2021). "This would lead to a displacement of miRNAs from miRNA/Ago2 complexes allowing the degradation of these miRNAs by RNase A. Among the tumor derived upregulated miRNAs, there were miRNAs with either tumor suppressor or oncogenic activity." (PMID 33435285, 2021). "A recent study has identified EGFR involvement in the suppression of tumor suppressor‐like miRNA maturation in response to hypoxic stress through phosphorylation of argonaute 2 (AGO2)." (PMID 33605506, 2021). "In this study, we answer those questions and reveal a mechanism that hypoxia in the tumor microenvironment is an incentive for mRNA turnover through inducing M1-Ubi modification of the key protein AGO2 in controlling the efficiency of the miRNA pathway." (PMID 34518544, 2021). "By coordinating the two mechanisms, MSI1/AGO2 complex enhances tumor proliferation and ensures cancer cell survival under hypoxia or chemodrug treatment." (PMID 31903115, 2020). "Studies on the effect of pterostilbene on BCSCs have shown that pterostilbene induces the expression of Argonaute2 (Ago2), a kind of interfering RNA, followed by increased levels of tumor-suppressive microRNAs miR-16, miR-141, miR-143, and miR-200c." (PMID 32952942, 2020). "Although how AGO2 coordinates its functions in response to stresses is still unclear, our findings highlighted a sophisticated mechanism by which MSI1/AGO2 complex promote tumor progression." (PMID 31903115, 2020). "Overexpressed C-terminus in tumor cells disrupts endogenous MSI1/AGO2 interaction and reduces tumor volume." (PMID 31903115, 2020). "For example, Chen reported that circAGO2 derived from the AGO2 gene can regulate the function of AGO2-miRNA complexes, and hence affect the tumor process." (PMID 32765960, 2020). "Nevertheless, phosphorylation at the critical Tyr393, Tyr529, or/and Tyr749 residues of AGO2 protein compels a tumor-promoting response." (PMID 32503341, 2020). "AGO2 is essential for MSI1 pro-tumor progression as its knockdown 31 inhibited the MSI1-enhanced tumor growth." (PMID 31903115, 2020). "Collectively, our findings demonstrated that disrupting MSI1/AGO2 interaction with MSI1-C-term decoy suppressed tumor growth by blocking the recruitment of AGO2 to its target mRNAs and subsequently altering their stability." (PMID 31903115, 2020). "Immunoprecipitation of MSI1 and AGO2 from the orthotropic xenograft tumor tissue confirmed the interaction between MSI1 and AOG2 in the MSI1-wt but not MSI1-NES-mut and MSI1-NLS-mut tumors." (PMID 31903115, 2020). "Result showed that in 80 of 85 (94%) matched tissue sets, AGO2 expression was significantly higher in tumor tissues than in normal tissues." (PMID 32420319, 2020). "The tumor sizes of mice bearing with SMMC-7721 control cells were obviously smaller than those with SMMC-7721 AGO2−/− cells." (PMID 32420319, 2020). "Disruption of AGO2 gene expression led to inhibition of HCC tumor proliferation and metastasis in vitro and in vivo." (PMID 32420319, 2020). "Cytosolic MSI1 enhances tumor proliferation and cancer cell survival through this AGO2-dependent mRNA regulation." (PMID 31903115, 2020). "In summary, our results show that miR-145-5p dependent tumor suppressor function is exerted only in presence of Ago2 protein expression." (PMID 30622242, 2019). "Our results highlight that the Ago2 protein in cancer cells strictly dictates miR-145-5p tumor suppressor activity." (PMID 30622242, 2019).